ZFYVE9 (zinc finger FYVE-type containing 9)
Description:
Early endosomal protein that functions to recruit SMAD2/SMAD3 to intracellular membranes and to the TGF-beta receptor. Plays a significant role in TGF-mediated signaling by regulating the subcellular location of SMAD2 and SMAD3 and modulating the transcriptional activity of the SMAD3/SMAD4 complex. Possibly associated with TGF-beta receptor internalization.
Synonyms: NSP; MADHIP; SARA; SMADIP; PPP1R173
Tractability: PROTAC: its protein half-life has been measured.
Gene: Protein-coding gene on chromosome 1 (52,141,888 to 52,348,671, forward strand). Ensembl gene ENSG00000157077.
Subcellular location: Cytoplasm; Early endosome membrane
Subcellular location (Human Protein Atlas): Cytosol; Vesicles
Pathways (Reactome):
Disease: SMAD2/3 Phosphorylation Motif Mutants in Cancer; TGFBR1 KD Mutants in Cancer
Signal Transduction: Downregulation of TGF-beta receptor signaling; TGF-beta receptor signaling activates SMADs
Gene Ontology:
Molecular function: 1-phosphatidylinositol binding; protein binding; protein domain specific binding; metal ion binding
Biological process: transforming growth factor beta receptor signaling pathway; endocytosis; endosomal transport
Cellular component: cytosol; early endosome membrane; protein-containing complex; early endosome; cytoplasm
Genetic constraint (gnomAD): Loss-of-function variants: 36 observed, 116.4 expected, observed/expected ratio (o/e) 0.31, 90% interval 0.24 to 0.41. The synonymous counts are far from expectation, so gnomAD's model fits this gene poorly and the ratio says little. Missense variants: 1,424 observed, 1,711.7 expected, observed/expected ratio (o/e) 0.83, 90% interval 0.8 to 0.87. Synonymous variants: 502 observed, 602.6 expected, observed/expected ratio (o/e) 0.83, 90% interval 0.77 to 0.9.
Homologues: Orthologues: chimpanzee ZFYVE9 (99% identical), macaque ZFYVE9 (95% identical), rabbit ZFYVE9 (92% identical), pig ZFYVE9 (91% identical), dog ZFYVE9 (88% identical), mouse Zfyve9 (87% identical), rat Zfyve9 (85% identical), guinea pig ZFYVE9 (83% identical), tropical clawed frog zfyve9 (61% identical), zebrafish zfyve9a (52% identical), zebrafish zfyve9b (30% identical), Drosophila melanogaster Sara (27% identical).
Diseases named in the same sentence as ZFYVE9 in open-access papers:
ZFYVE9 is named in the same sentence as 11 diseases in open-access papers, as found by Europe PMC text mining. Sharing a sentence is not in itself a finding about the gene and the disease. The quoted sentences say what the papers report.
aortic aneurysm (2 papers, 2016 to 2018). A ruptured aneurysm located in the wall of the proximal portion of the descending aorta proceeding from the arch of the aorta. "We point to candidate genes of comorbidity in TS e.g. congenital urinary malformations (PRKX), premature ovarian failure (KDM6A) and aortic aneurysm (ZFYVE9 and TIMP1)." (PMID 27687697, 2016). "Additionally, the implementation of genetic testing to identify genes associated with malformations (ZFYVE9, TIMP1, PRKX, KDM6A) can lead to a higher detection rate of aortic aneurysm formation, congenital urinary malformations and other anomalies." (PMID 29537378, 2018). "We describe novel candidate genes that could be involved in comorbidity in TS and explain congenital urinary malformations (PRKX), premature ovarian failure (KDM6A), and aortic aneurysm formation (ZFYVE9 and TIMP1)." (PMID 27687697, 2016).
dilatation (2 papers, 2016 to 2020). "ZFYVE9 recruits SMAD2 to the TGF-β receptor and was differentially expressed and contributed to aortic dilatation in turner syndrome." (PMID 33083483, 2020). "Therefore, we find it intriguing that ZFYVE9, which recruits SMAD2 to the TGF-β receptor, was differentially expressed and therefore could contribute to aortic dilatation in TS." (PMID 27687697, 2016).
Aortic dissection (1 paper, 2022). Aortic dissection refers to a tear in the intimal layer of the aorta causing a separation between the intima and the medial layers of the aorta. "New genes (MLX, DAB2IP, EP300, ZFYVE9, PML, PRKCD) were suggested as candidate aortic dissection-associated genes, through correlation analyses performed on the results of a WES study on a cohort of 99 Chinese cases." (PMID 35892496, 2022).
pulmonary fibrosis (1 paper, 2023). Chronic progressive interstitial lung disorder characterized by the replacement of the lung tissue by connective tissue, leading to progressive dyspnea, respiratory failure, or right heart failure. "Compared with the control group, the BLM-induced pulmonary fibrosis group exhibited significantly higher expression of Fmod and Tgfbr2 mRNA; in contrast, the mRNA expression levels of Bambi, Skp1, Zfyve9, Zfyve16, Ppp2ca, Ppp2r1a, Ppp2r1b, Rps6kb1, and Rps6kb2 were markedly lower." (PMID 38259493, 2023).
tumor (2 papers, 2013 to 2021). "Of note, we identified newly emerged 8 non-synonymous somatic mutations of the genes (ACAP2, CARD10, KIAA0556, PAAQR7, PPP1R39, SAFB2, STARD9, and ZFYVE9) in the imatinib-resistant tumor tissue." (PMID 23922791, 2013).
cancer (1 paper, 2021). A tumor composed of atypical neoplastic, often pleomorphic cells that invade other tissues. "KEGG analysis showed that ACVR1, SMAD1, ZFYVE9, BMPR1B, and TGFB3 were related to regulating proteoglycan in cancer, focal adhesion, tight junction, PI3K-Akt signaling pathway, cell adhesion molecules (CAMs), Rap1 signaling pathway, osteoclast differentiation, and Hippo signaling pathway." (PMID 34725559, 2021).
ZFYVE9 also shares sentences with these, for which no sentence is quoted: infection (1 paper); Obesity (1); Pancreatic Cancer (1); premature ovarian failure (1); Turner syndrome (1).